LINC02499 (long independently transcribed non-coding RNA 2499)
Gene: Long non-coding RNA gene on chromosome 4 (73,508,232 to 73,534,128, forward strand). Ensembl gene ENSG00000250436.
Diseases named in the same sentence as LINC02499 in open-access papers:
LINC02499 is named in the same sentence as 4 diseases in open-access papers, as found by Europe PMC text mining. Sharing a sentence is not in itself a finding about the gene and the disease. The quoted sentences say what the papers report.
liver cancer (1 paper, 2021). An epithelial or non-epithelial malignant neoplasm that arises from the liver. "As further verification of this finding, the difference in LINC02691, LINC02499, LINC01354, and NAV2-AS4 expression in liver cancer tissues (n = 371) was statistically significant (p < 0.05) compared with normal liver tissues (n = 50)." (PMID 34141458, 2021).
tumor (3 papers, 2020 to 2024). "For example, some lncRNAs, such as NOC2L-4.1, TUG1, and MALAT1, are well established to promote tumour growth, while other lncRNAs, such as ASMTL-AS1, LINC02381, and LINC02499 have been found to inhibit tumour progression." (PMID 33243205, 2020). "This could suggest a potentially universal role of LINC02499 as a tumor suppressor across different cancer types." (PMID 38568288, 2024).
LINC02499 also shares sentences with these, for which no sentence is quoted: cancer (1 paper); hepatocellular carcinoma (1).